S100A4 (S100 calcium binding protein A4)
Diseases named in the same sentence as S100A4 in open-access papers (continued):
Sharing a sentence is not in itself a finding about the gene and the disease.
breast carcinoma (continued). "Extracellular ATP induced breast cancer and fibroblast cells to release S100A4, which promoted cancer cell metastasis." (PMID 31754326, 2019). "Identically to CYR61, S100A4 is upregulated during EMT programs in breast cancer and correlates with bone metastasis." (PMID 31709177, 2019). "We showed that reversing EMT-induced upregulation of CYR61 and S100A4 leads to reduced invasive behavior in breast cancer cells in different invasion setups." (PMID 31709177, 2019). "In this study, we found that a highly bone-metastatic subline of MDA-MB-231 breast cancer cells released more S100A4 than the parental cells and had a greater stimulatory effect on osteoclastogenesis." (PMID 31667000, 2019). "Reducing S100A4 expression leads to decreased 3 D spheroid invasion and invasiveness of breast cancer cells in co-culture with osteosarcoma cells." (PMID 31709177, 2019). "In this study, we further investigate the role of S100a4, a gene previously reported to be differentially expressed in highly metastatic mouse mammary carcinomas." (PMID 31881983, 2019). "One revealed mechanism is that STAT4 can activate the S100A4 promoter by interacting with HBXIP, which increases the expression of S100A4 and enhances the proliferation and migration of breast cancer cells." (PMID 30987235, 2019). "S100A4 belongs to the S100 family of EF hand calcium-binding proteins and has been shown to promote metastasis in a model system of breast cancer." (PMID 31895690, 2019). "The calcium-binding protein S100A4 and cell adhesion protein fibronectin were both expressed at low levels in primary mammary tumours and increased in bone metastasis." (PMID 31783893, 2019). "Our previous work showed that a fusogenic liposome can deliver anti-S100A4 into the cytoplasm in a fusion-dependent manner bypassing the cellular endocytosis and avoid the inefficient escape in breast cancer." (PMID 30127784, 2018). "In this study, we explored the effect of extracellular S100A4 on breast cancer cells (BCCs) of different subtypes and investigated their further interactions with myeloid cells." (PMID 29741811, 2018). "Supportive evidence is presented by recent work demonstrating reduced migration and metastases of breast cancer cells following down-modulation of S100A4." (PMID 29329589, 2018). "The overexpression of S100A4 as an indicator of poor prognosis and high metastatic potential was first proposed in human breast cancer." (PMID 29069865, 2017). "Previous studies have shown that expression of S100a4 leads to acquisition of some mesenchymal characteristics in the mammary carcinoma cells." (PMID 29162812, 2017). "For example, in the early stage of breast cancer, the expression of S100A4 with that of either hepatocyte growth factor receptor (HGFR) or osteopontin (OPN) was an indicator of tumor metastasis and poor prognosis." (PMID 29069865, 2017). "The results suggested that mRNA level and protein level expression of S100A4 are functional distinct in breast cancer." (PMID 28051137, 2017). "Breast cancer cells with S100A4 overexpression were shown to be markedly more invasive than the non-transfected controls." (PMID 28824547, 2017). "Levels of S100A4 have been shown to be induced in human breast cancer interstitial fluid and in the plasma of S100A4 transgenic mice." (PMID 29069865, 2017).
breast carcinoma (continued). "S100A4 is one of the numerous specific metastasis-related proteins, which was synthesized as a 9,000 molecular weight acidic polypeptide (p9ka/S100A4) by the elongated myoepithelial-like cells in a rat mammary tumor cell line culture." (PMID 29069865, 2017). "In summary, we have demonstrated that knockdown of AKT3 regulates migration in TNBC breast cancer cells via upregulation of S100A4." (PMID 26741489, 2016). "Conversely, recent analysis of protein expression in the MDA-MB-231BR breast cancer cell line metastatic to mouse brains showed that S100A4 was under expressed compared to the parent MDA-MB-231 line." (PMID 27100728, 2016). "S100A4 is a small calcium-binding protein that has been shown to promote migration, invasion, and anchorage-independent growth of breast cancer cells." (PMID 25776572, 2015). "By contrast, high S100A4 expression has been observed in breast cancer, colorectal tumors, gastric cancer, pancreatic carcinoma, esophageal squamous cell carcinoma and osteosarcoma cells." (PMID 25339497, 2015). "The S100A4 blocking antibody (6B12) reduces tumor growth and metastasis in a model of spontaneous breast cancer." (PMID 25884510, 2015). "Briefly, the metastatic CSML100 mammary carcinoma cells displayed a suppressed ability to form metastases when grafted to S100A4(-/-) mice." (PMID 25884510, 2015). "Recently, we have shown that the S100A4 function-blocking antibody (6B12) suppressed metastasis formation in mice grafted with metastatic mammary cancer cells." (PMID 25884510, 2015). "This group recently used the orthotopic 4T1 breast cancer model to show that depletion of S100A4 cells reduced the metastatic area, increased apoptosis in metastases, and reduced CD31 staining." (PMID 22509805, 2012). "Noteworthy, the levels of S100A4 mRNA are higher in breast carcinomas than in benign breast tumour specimens." (PMID 21629247, 2011). "A pivotal role of metastasis-inducing S100A4 in the development of tumor stroma has been proven in animal models and verified in human breast cancer biopsies." (PMID 20442771, 2010). "In conclusion S100A4 protein expression appears to be expressed widely in early and advanced stages of breast cancer compared with normal breast." (PMID 18771601, 2008). "The purpose of the study was to determine the expression of S100A4 protein in the invasion status and metastatic potential of breast cancer by using tissue microarray and to determine its role in breast cancer based on the expression of S100A4 gene product." (PMID 18771601, 2008). "The reduced invasive potential of MDA/RLN2 transfectants in vitro suggested that the reduction in cellular motility through down-regulation of S100A4 was the dominant mechanism of relaxin's long-term effect on MDA-MB-231 breast cancer cells." (PMID 18718015, 2008). "We had previously reported that relaxin down-regulated S100A4 in MDA-MB-231 and in a stable MDA/RLN2 transfectant, thus, identifying S100A4 as a novel target gene for relaxin in breast cancer cells." (PMID 18718015, 2008). "S100A4 gene occurs in cluster of 13 S100 genes on chromosome 1, which are also often amplified in cancer of the breast and which contains jumping elements." (PMID 18771601, 2008). "Five of 37 (13.5%) cases in the paired samples (primary breast carcinoma and matched lymph nodes) showed presence of S100A4 protein in the primary site, while 13/37 (35.1%) cases showed S100A4 in lymph node." (PMID 18771601, 2008). "A comparable observation, although verified only by immunological methods, was made when S100A4 from tumor interstitial fluid from breast cancer patients was separated by 2D-PAGE." (PMID 18554396, 2008). "Expression of the S100A4 protein is positively correlated with breast cancer invasiveness of rodent mammary carcinoma cells and serves as an independent prognostic marker that is highly significant for poor survival in breast cancer patients." (PMID 18718015, 2008).
breast carcinoma (continued). "We were able to demonstrate a similar down-regulation of S100A4 protein in ERα-positive T47D human breast cancer cells after 48 hours and 72 hours of RLN2 exposure." (PMID 18718015, 2008). "S100A4 protein expression appears widely expressed in early and advanced breast cancer stages compared with normal breast." (PMID 18771601, 2008). "This demonstrated for the first time that S100A4 is a relaxin target molecule in vitro and in vivo in human breast cancer cells." (PMID 18718015, 2008). "Oligonucleotide primers employed at melting temperatures (TM in °C) used to determine the expression of RLN2, human RXFP1 relaxin receptor (RXFP1), S100A4 and 18S transcripts in human breast cancer cell lines and xenograft tumours." (PMID 18718015, 2008). "S100A4 was expressed in a higher percentage in breast cancer tissue compared to normal tissue which showed direct correlation of S100A4 protein in infiltrating breast cancer node negative." (PMID 18771601, 2008). "In conclusion, the in vitro and in vivo down-regulation of S100A4 identifies a new and potentially clinically relevant property of relaxin in human breast cancer." (PMID 18718015, 2008). "T47D human breast cancer cells exposed to 100 ng/ml and 500 ng/ml rhRLN2 for 72 hours also responded with a reduction in S100A4 protein with 500 ng/ml rhRLN2 already being effective after 48 hours of exposure." (PMID 18718015, 2008). "Support for S100A4 as a prognostic marker was first obtained from two studies of patients with early stages of breast cancer." (PMID 15900299, 2005). "Previous immunohistochemical studies of S100A4 showed an overexpression in 41% of breast carcinomas, 55% of gastric carcinomas, 94% of colorectal adenocarcinomas, 93% of invasive pancreatic carcinomas, and 25% of oesophageal squamous carcinoma." (PMID 16265347, 2005). "The S100A4 content of the mouse cell lines varied from about a tenth to over three times that of the known low S100A4-expressing control Rama 25 cell line isolated from a dimethyl benzanthracene-induced rat mammary tumour." (PMID 14710237, 2004). "Taken together, our results seem to question the prognostic value of S100A4 in breast cancer patients, and further investigations are warranted to elucidate the importance of this S100 protein as a prognostic factor." (PMID 12439718, 2002). "Surprisingly, for stage I and II breast carcinoma patients S100A4 was found to be the most significant predictor of patient survival, also compared to the well documented clinical and pathological parameters." (PMID 12439718, 2002). "An inverse correlation between S100A4 and members of the cadherin–catenin complex has recently been shown in gastric cancer and NSCLC, and S100A4 and E-cadherin have been reported to be inversely regulated in a murine mammary carcinoma cell line." (PMID 12439718, 2002). "The observed inverse correlation between S100A4 and ER is in agreement with previous expression studies performed on human breast cancer specimens." (PMID 12439718, 2002). "In 66 breast cancer biopsies, the expression of the Ca2+-binding protein S100A4, E-cadherin, α- and β-catenin was examined by immunohistochemistry, and the results were related to clinical and pathological parameters." (PMID 12439718, 2002). "In their study, S100A4 was the most significant predictor of patient survival in a panel of 349 stage I and II breast cancer patients." (PMID 12439718, 2002). "Of the 66 breast carcinomas in our tumour material, only 62 were available for analysis of S100A4 immunoreactivity." (PMID 12439718, 2002). "A similar result was obtained when transgenic mice bearing the mouse S100A4 transgene were mated with a strain of mice which yielded MMTV-induced mammary tumours." (PMID 11875708, 2002). "S100A4 has been shown to be a chemoattractant for T cells in the context of breast cancer lung metastasis, though the receptor mediating this interaction is unknown." (PMID 40078995, 2025).
breast carcinoma (continued). "Although no previous reports have linked S100A4 to aging, S100A4 has been extensively studied for its role in promoting the proliferation of breast cancer cells, liver cancer cells, lung cancer cells, prostate cells, and endometrial cancer cells." (PMID 39664902, 2024). "S100A4 knockdown diminishes stanniocalcin 1-induced lung metastasis of breast cancer." (PMID 39830522, 2024). "A study reported that S100A4 mediates the effect of STC1 on angiogenesis in breast cancer." (PMID 38962272, 2024). "Moreover, S100A4 was reported to be a substrate of TGase 2 and the TGase 2-catalyzed cross-linking of S100A4 had a positive impact on the migration behavior of mammary tumor cells." (PMID 38165538, 2024). "Furthermore, the pro-metastatic microenvironmental factor S100A4 was described to stimulate basal-like breast cancer cells to secrete pro-inflammatory cytokines that convert monocytes into TAM-like cells." (PMID 37340387, 2023). "We found that the functions of STC1 in breast cancer cells are mediated by S100A4." (PMID 37400459, 2023). "We further determined whether S100A4 is involved in mediating the functions of STC1 in promoting the aggression of breast cancer cells, the tubule formation of HUVECs, and the chemotactic migration of lung fibroblasts." (PMID 37400459, 2023). "Previous studies have shown that the inhibition of S100A4 could inhibit the invasion ability of breast cancer cells through EMT and regulate MMP2 in breast cancer to participate in EMT." (PMID 37033662, 2023). "Results in vivo with the mouse cell line 4T1 which was isolated from a spontaneously metastatic mouse TNBC tumour, and which depends on the expression of S100A4 for its metastatic potential are largely consistent with those obtained in vitro with the rat and human breast cancer cell lines." (PMID 37509135, 2023). "S100A4 has the function of promoting angiogenesis, and our study indicated that S100A4 could mediate the pro-angiogenic function of breast cancer cells with high STC1 expression." (PMID 37400459, 2023). "While an increase of KDM3A is concomitant with a reduced H3K9me2/3 during breast tumorigenesis, KDM3A facilitated the activation of genes implicated in breast cancer as MYC, PAX3, Cyclin D1, MMP-9, S100A4, and JUN, thereby enhancing the proliferation and motility of breast cancer cells." (PMID 36185256, 2022). "S100A4 is suggested to play a leading role in breast cancer invasion." (PMID 35546077, 2022). "Breast cancer cell-derived exosomes were used to deliver S100A4 siRNA that led to significantly reduced postoperative breast cancer metastasis, and exosomes loaded with SCD-1 siRNA significantly promoted anaplastic thyroid carcinoma cell apoptosis by enhancing its intracellular ROS level." (PMID 36119094, 2022). "Furthermore, several reports have also highlighted a significant correlation between the expression of S100A4 and advanced tumor stage, the presence of distant metastases, and worse survival rates in breast cancer patients." (PMID 33946884, 2021). "Indeed, small‐EVs from breast cancer MDA‐MB231 sub‐cell line (4175) localized to the lungs following IV (retro‐orbital) administration with uptake by S100A4+ fibroblasts and surfactant protein C+ epithelial cells." (PMID 34194679, 2021). "Increased FA levels are found in various TME such as breast cancers, thus our findings suggest that blocking S100A4/PPAR-γ pathway in such cancer types with FA-enriched TME may have better effects than in cancers with nutrient-stressed TME." (PMID 34145030, 2021). "In addition, administration of the SERCA inhibitor thapsigargin inhibits S100A4 protein expression in MDA-MB-231 breast cancer cells." (PMID 33806911, 2021). "Hence, it is not clear that Chk1 inhibitor suppressed the invasiveness of breast cancer cells via just the expression of S100A4." (PMID 34124754, 2021). "Moreover, down-regulation of S100A4 in breast cancer cells decreased EMT by suppressing the expression of MMP2." (PMID 33549040, 2021).
breast carcinoma (continued). "Some of the modulated proteins found in the present study such as haptoglobin or S100A4 have been related to CMT or human breast cancer previously, while others such as kallikrein-1 and immunoglobulin gamma-heavy chains A and D are described here for the first time." (PMID 32344524, 2020). "Likewise, extracellular S100A4 indirectly interfering with the differentiation of myeloid cells by activating breast cancer cells to elevate secretion of pro‐inflammatory cytokines that convert monocytes into the tumour‐associated macrophages." (PMID 32307910, 2020). "Adding extracellular CYR61 to breast cancer spheroids with transient decreased S100A4 expression could restore the effect und led to a slightly increased invaded area." (PMID 31709177, 2019). "The function of S100A4 in the metastasis of breast cancer is not limited to bone." (PMID 31667000, 2019). "S100A4 mediates breast cancer metastasis, and its expression is controlled via the β‐catenin pathway; therefore, high levels of KLK6 could activate the β‐catenin pathway as reported in keratinocytes, to drive the expression of S100A4." (PMID 30980596, 2019). "A previous study has demonstrated that breast cancer cells could release S100A4 to stimulate SAA1 and SAA3 expression via an autocrine manner, and that SAA1/SAA3 could promote metastasis of breast cancer cells." (PMID 31390756, 2019). "In conclusion, this study revealed that OSX could potentiate breast cancer cell migration and tumor angiogenesis by up‐regulating S100A4 expression in vitro and in vivo." (PMID 30450809, 2019). "We could identify a close correlation between CYR61 and S100A4 expression and breast cancer invasion and metastasis in breast cancer patients." (PMID 31709177, 2019). "In this study, we found that S100A4 is secreted from bone-metastatic breast cancer cells." (PMID 31667000, 2019). "It was shown that S100A4 facilitates breast cancer invasion." (PMID 31709177, 2019). "Moreover, several studies have reported that S100A4 regulates breast cancer cell migration to other organs in animal models." (PMID 31667000, 2019). "Consequently, we examined the value of CYR61 and/or S100A4 as a potential therapeutic target for advanced breast cancer." (PMID 31709177, 2019). "Because of S100A4 role in breast cancer metastasis, we pursued it further." (PMID 31844158, 2019). "S100A4 expression was also increased in breast cancer that metastasized to lung, brain, and liver." (PMID 31667000, 2019). "Furthermore, a search of NCBI GEO microarray data sets of tumor samples from 65 breast cancer patients (GSE 14020) revealed a significantly higher expression of S100A4 in bone-metastasized tumors than in tumors metastasized to other organs." (PMID 31667000, 2019). "Using immunohistochemical staining, we examined whether OSX expression is correlated with S100A4 expression in breast cancer samples." (PMID 30450809, 2019). "For example, it has been reported that S100A4, a small Ca2+-binding protein secreted by various cells into the tumor microenvironment, could activate breast cancer cells, especially the TNBC type, to promote macrophage conversion into the M2 type 25." (PMID 31528210, 2019). "Moreover, OSX expression was significantly positively correlated with the level of S100A4 in breast cancer tissues." (PMID 30450809, 2019). "Collectively, these results indicated that bone-metastasized breast cancer cells have high levels of S100A4 gene expression and protein secretion and that S100A4 secretion may be associated with cancer-induced osteoclastogenesis." (PMID 31667000, 2019). "CYR61 and S100A4 are drivers for breast cancer cell invasion in vitro." (PMID 31709177, 2019). "Next, we investigated whether S100A4 was responsible for the stimulation of osteoclastogenesis by bone-metastatic breast cancer cells." (PMID 31667000, 2019).